ATG14 (autophagy related 14)
Description:
Required for both basal and inducible autophagy. Determines the localization of the autophagy-specific PI3-kinase complex PI3KC3-C1. Plays a role in autophagosome formation and MAP1LC3/LC3 conjugation to phosphatidylethanolamine. Promotes BECN1 translocation from the trans-Golgi network to autophagosomes. Enhances PIK3C3 activity in a BECN1-dependent manner. Essential for the autophagy-dependent phosphorylation of BECN1. Stimulates the phosphorylation of BECN1, but suppresses the phosphorylation PIK3C3 by AMPK. Binds to STX17-SNAP29 binary t-SNARE complex on autophagosomes and primes it for VAMP8 interaction to promote autophagosome-endolysosome fusion. Modulates the hepatic lipid metabolism (By similarity).
Synonyms: Barkor; Atg14L; KIAA0831
Tractability: Small molecule: a structure with a bound ligand is known. Antibody: UniProt places it where antibodies can reach, with high confidence. PROTAC: UniProt records ubiquitination sites on it; ubiquitination databases record sites on it.
Gene: Protein-coding gene on chromosome 14 (55,366,391 to 55,411,830, reverse strand). Ensembl gene ENSG00000126775.
Subcellular location: Cytoplasm; Endoplasmic reticulum membrane; Preautophagosomal structure membrane; Cytoplasmic vesicle, autophagosome membrane
Subcellular location (Human Protein Atlas): Plasma membrane; Vesicles
Pathways (Reactome):
Disease: Dengue virus modulates apoptosis; SARS-CoV-2 activates/modulates innate and adaptive immune responses
Autophagy: Macroautophagy
Immune System: Antigen Presentation: Folding, assembly and peptide loading of class I MHC
Gene Ontology:
Molecular function: GTPase binding; phosphatidylinositol 3-kinase inhibitor activity; protein binding; protein-membrane adaptor activity; phosphatidylinositol 3-kinase regulator activity
Biological process: autophagosome assembly; autophagosome maturation; autophagosome membrane docking; cellular response to starvation; early endosome to late endosome transport; endosome to lysosome transport; macroautophagy; mitophagy; phosphatidylinositol 3-kinase/protein kinase B signal transduction; phosphatidylinositol-3-phosphate biosynthetic process; post-transcriptional regulation of gene expression; regulation of macroautophagy; regulation of protein complex stability; response to mitochondrial depolarisation; cellular response to glucose starvation; negative regulation of protein phosphorylation; positive regulation of protein phosphorylation; protein targeting to lysosome; autophagy
Cellular component: autophagosome; cytoplasm; endoplasmic reticulum membrane; extrinsic component of omegasome membrane; extrinsic component of phagophore assembly site membrane; phagophore assembly site; phagophore assembly site membrane; phosphatidylinositol 3-kinase complex, class III; axoneme; cytosol; autophagosome membrane; mitochondria-associated endoplasmic reticulum membrane contact site; phagocytic vesicle
Genetic constraint (gnomAD): Loss-of-function variants: 26 observed, 48.52 expected, observed/expected ratio (o/e) 0.54, 90% interval 0.39 to 0.74. The upper end of that interval is the gene's LOEUF score, 0.74, which puts it in group 3 of 6, group 1 being the genes least tolerant of losing a copy. Missense variants: 583 observed, 581.53 expected, observed/expected ratio (o/e) 1, 90% interval 0.94 to 1.07. Synonymous variants: 219 observed, 221.72 expected, observed/expected ratio (o/e) 0.99, 90% interval 0.88 to 1.11.
Homologues: Orthologues: chimpanzee ATG14 (99% identical), macaque ATG14 (99% identical), pig ATG14 (96% identical), dog ATG14 (96% identical), mouse Atg14 (93% identical), guinea pig ATG14 (93% identical), rat Atg14 (92% identical), rabbit ATG14 (84% identical), tropical clawed frog atg14 (78% identical), zebrafish atg14 (65% identical), Drosophila melanogaster Atg14 (26% identical).
Diseases named in the same sentence as ATG14 in open-access papers:
ATG14 is named in the same sentence as 63 diseases in open-access papers, as found by Europe PMC text mining. Sharing a sentence is not in itself a finding about the gene and the disease. The quoted sentences say what the papers report.
hepatocellular carcinoma (11 papers, 2021 to 2025). A malignant tumor that arises from hepatocytes. "It has also been reported that ADRB2 interferes with the autophagy of the Beclin1/VPS34/Atg14 complex in hepatocellular carcinoma, resulting in the reprogramming of glucose metabolism and the acquisition of sorafenib resistance." (PMID 36406346, 2022). "ATG14 not only plays a crucial role in autophagy initiation but also participates in tumor growth and drug resistance in colorectal cancer, ovarian cancer, hepatocellular cancer, and pancreatic cancer." (PMID 39814232, 2025). "YTHDF1, induced by HIF-1α, promotes hypoxia-induced autophagy and hepatocellular carcinoma malignancy through m6A-modified ATG2A and ATG14 dependency." (PMID 40251202, 2025). "For instance, HIF-1α has been shown to directly stimulate the transcription of YTHDF1, thereby facilitating hepatocellular carcinoma (HCC) autophagy and malignancy by enhancing the translation of ATG2A and ATG14." (PMID 40136363, 2025). "Additionally, the reader YTHDF1 could promote translation of autophagy-related genes ATG2A and ATG14 by binding to m6A-modified ATG2A and ATG14 mRNA, which facilitated autophagy and autophagy-related human hepatocellular carcinoma progression." (PMID 36347025, 2022). "In hepatocellular carcinoma (HCC), interferon-related developmental regulator 1 (IFRD1) is upregulated by glutamine starvation to inhibit autophagy by promoting TRIM21-mediated degradation ATG14." (PMID 40735642, 2025).
gastric cancer (9 papers, 2022 to 2025). A primary or metastatic malignant neoplasm involving the stomach. "The overexpression of lncRNAs in drug-resistant gastric cancer cells has been found to reduce the degradation of ATG14 mRNA by sequestering MIR188-3p, leading to the activation of autophagy and chemotherapy immunity." (PMID 40299524, 2025). "For example, lncRNA EIF3J-DT increases ATG14 expression by sequestering miR-188-3p and activates autophagy, leading to drug resistance in gastric cancer cells." (PMID 37035213, 2023). "As a competing endogenous RNA for miR-497-5p, LINC01572 decreased miR-497-inhibitory 5p’s impact on ATG14, resulting in chemo-induced autophagy and the chemoresistance of gastric cancer (GC) cells." (PMID 36983670, 2023). "EIF3J divergent transcript (EIF3J-DT) is highly expressed in gastric cancer cells with chemotherapeutic drugs, and EIF3J-DT specifically regulates ATG14 expression, activates autophagy, and induces drug resistance in gastric cancer cells." (PMID 38481525, 2024). "In gastric cancer, EIF3J-DT is involved in the regulation of autophagy and chemical resistance of gastric cancer cells by targeting ATG14, while autophagy-dependent apoptosis has been shown to be a promising therapeutic target in COAD." (PMID 36844874, 2023). "Furthermore, LncRNA EIF3J-DT (eukaryotic translation initiation factor 3 subunit J divergent transcript) exhibited high expression in drug-resistant gastric cancer cells and was involved in regulating autophagy and chemotherapy resistance by targeting ATG14 (autophagy-related 14)." (PMID 39532842, 2024).
pancreatic cancer (9 papers, 2020 to 2025). "PVT1 can stimulate the Wnt/β-catenin signaling pathways and autophagy through the function of miR-619-5p in the miR-619-5p/autophagy-related 14 (ATG14) and miR-619-5p/pygopus homolog 2 (Pygo2) axes, causing chemo-resistance promotion in pancreatic cancer." (PMID 38559560, 2024). "The lncRNA-PVT1/miR-619-5p/Pygo2/ATG14 axis was shown to be critical for the promotion of gemcitabine chemoresistance of pancreatic cancer." (PMID 35371339, 2022). "We also indicated that PVT1 modulates gemcitabine resistance by the miR-619-5p/Pygo2 and miR-619-5p/ATG14 axes in pancreatic cancer cells." (PMID 32727463, 2020). "Taken together, our data demonstrated that PVT1 functions as a ceRNA to regulate the miR-619-5p/Pygo2 and miR-619-5p/ATG14 axes to improve pancreatic cancer chemoresistance." (PMID 32727463, 2020). "In addition, ATG14 promotes platinum drugs and gemcitabine resistance in colorectal cancer, pancreatic cancer, ovarian cancer, and lung cancer." (PMID 39814232, 2025). "However, multi-IHC revealed elevated ULK1 protein levels and activity, marked by phosphorylated ATG14 (pATG14), particularly in high-grade (grade 3) pancreatic tumors compared with normal tissues." (PMID 41408407, 2025). "One study found that PVT1/miR-619-5p/Pygo2 and PVT1/miR-619-5p/ATG14 regulatory axes could mediate gemcitabine resistance in pancreatic cancer cells by activating Wnt/β-catenin signaling pathway and autophagy signaling pathway respectively." (PMID 38811958, 2024). "In addition, lncRNA PVT1 was observed to promote autophagy and gemcitabine resistance in pancreatic cancer by regulating miR-619-5p/ATG14 via the Wnt/β-catenin pathway." (PMID 36899946, 2023). "Moreover, upregulated PVT1 can activate Wnt/β-catenin signaling pathway by regulating expression of both Pygo2 and ATG14 and thus promote autophagy related complex in pancreatic cancer." (PMID 35392800, 2022). "Furthermore, PVT1 also took part in drug resistance of pancreatic cancer by interacting with ATG14 and promoting PtdIns3K activity." (PMID 33868366, 2021). "We also found that PVT1/miR-619-5p could target ATG14 and promote cellular autophagic activity, and pharmacological or genetic inhibition of autophagy activity restored pancreatic cancer gemcitabine sensitivity." (PMID 32727463, 2020). "It was also found that the interaction of PVT1 and ATG14 facilitates the formation of the autophagy-specific complex I (PtdIns3K-C1) and class III PtdIns3K activity, thereby initiating autophagy in pancreatic cancer." (PMID 36899946, 2023).
ovarian carcinoma (8 papers, 2016 to 2025). A malignant neoplasm originating from the surface ovarian epithelium. "Up-regulation of both EGR1 and miR-152 inhibit the downstream target genes of miR-152, and ATG14, thus suppressing cisplatin resistance in ovarian cancer cells by preventing protective autophagy in ovarian cancer cells." (PMID 38244586, 2024). "For example, ATG14 (2.5%) plays important roles in promoting membrane tethering and fusion of autophagosomes and endolysosomes, and downregulation of ATG14 can make it sensitized to cisplatin-induced apoptosis in ovarian cancer." (PMID 36831585, 2023). "The findings suggested that miR-129 inhibited the autophagy of ovarian cancer cells by directly targeting ATG14." (PMID 33637694, 2021). "Over-expression of miR-152 sensitizes ovarian cancer cells to cisplatin-induced apoptosis by inhibiting ATG14 expression and autophagy-induced cyto-protection." (PMID 27825125, 2016). "Moreover, the down-regulation of ATG14 by EGR1-miR152 was shown to sensitize ovarian cancer cells to cisplatin-induced apoptosis by inhibiting cytoprotective autophagy." (PMID 32727463, 2020). "Equally, a recent study has provided evidence that the downregulation of autophagy-related gene 14 (ATG14) and Forkhead box protein P1 (FOXP1), a well-known transcription factor with oncogenic effects in ovarian cancer cells, can enhance the sensitivity of ovarian cancer cells to cisplatin." (PMID 38994937, 2024).
colorectal cancer (6 papers, 2017 to 2025). A primary or metastatic malignant neoplasm that affects the colon or rectum. "Specifically, we demonstrate that EA meliorates inflammation and promotes autophagy in colorectal cancer via SIRT1/miR-215/Atg14 Axis." (PMID 38006398, 2023). "For example, lncRNA-SNHG14 was shown to stimulate cell autophagy to facilitate cisplatin resistance of colorectal cancer by regulating the miR-186/ATG14 axis." (PMID 34539244, 2021). "In the same work, SNHG14 inhibited miR-186, which blocked ATG14 expression in cisplatin-resistant colorectal cancer cell lines." (PMID 33117715, 2020). "In the present study, we found that BTG1 overexpression up-regulated the expression of ATG7, ATG14 and Beclin-1 in both colorectal cancer cells." (PMID 27447746, 2017). "Using azoxymethane/dextran sulfate sodium- (AOM/DSS-) induced colorectal cancer model in mice, we explored whether EA treatment can inhibit inflammation and promote autophagy via the SIRT1/miR-215/Atg14 axis." (PMID 38006398, 2023). "In colorectal cancer biopsies, high expression of SNHG14 and ATG14 was observed." (PMID 33117715, 2020).
breast carcinoma (5 papers, 2017 to 2026). "Beclin-1 is frequently monoallelically deleted in breast cancer and interacts with ATG14 to trigger apoptosis inhibition in breast cancer, leading to cancer progression and chemotherapy resistance." (PMID 40426890, 2025). "We show that the dissociation of Bcl-2 from Beclin 1 and subsequent enhancement of interaction among the ATG14-Beclin1-PI3KC3 complex lead to the induction of protective autophagy in TAM-resistant breast cancer cells." (PMID 28431397, 2017).
atherosclerosis (4 papers, 2022 to 2024). A disease characterized by the build-up of fatty material and calcium deposition in the arterial wall resulting in partial or complete occlusion of the arterial lumen. "In mice and in vitro models, the macrophage-specific downregulation of ATG14/ATG14 expression (a key protein in autophagy) promoted atherosclerosis due to oxLDL accumulation and the induction of inflammation." (PMID 39528464, 2024).
diabetes (4 papers, 2017 to 2022). "Furthermore, TEM data demonstrated a significant reduction in autophagosome/autolysosome formation in diabetes patients, strongly supporting a correlation between miR199a-5p/ATG14-mediated autophagy and hepatic insulin sensitivity in diabetes patients." (PMID 29540751, 2018). "Finally, we detected upregulated miR199a-5p levels, which were correlated with reduced ATG14 mRNA levels and downregulated autophagy in liver samples obtained from diabetes patients." (PMID 29540751, 2018). "More importantly, we demonstrated that in type 2 diabetes patients and animal models the hepatic miR199a-5p level is upregulated, whereas the ATG14 level and autophagy levels are suppressed, which implies the importance of the miR199a-5p/ATG14 axis in translational diabetes research." (PMID 29540751, 2018). "Our study also demonstrated the significance of the miR199a-5p/ATG14 axis in translational diabetes research, which may serve as a potential therapeutic target for hepatic insulin sensitivity and other associated metabolic diseases." (PMID 29540751, 2018). "Importantly, we provided evidence of increased hepatic miR199a-5p levels in diabetes patients, which correlated with decreased ATG14 levels and autophagy." (PMID 29540751, 2018). "Therefore, we further proposed a miR199a-5p/ATG14/autophagy/insulin resistance axis in diabetes pathogenesis in our study." (PMID 29540751, 2018).
osteosarcoma (4 papers, 2014 to 2026). A usually aggressive malignant bone-forming mesenchymal neoplasm, predominantly affecting adolescents and young adults. "In the present study, the hypothesis that silencing of Barkor/ATG14 sensitizes cisplatin-resistant osteosarcoma cells to ER stress-associated apoptosis was tested and verified." (PMID 24337183, 2014). "Therefore, we investigated whether knockdown of Beclin1-associated autophagy-related key regulator (Barkor/ATG14) promoted cisplatin-induced apoptosis in a drug-resistant osteosarcoma cell line in vitro." (PMID 24337183, 2014). "On the other hand, a previous study reported that MARCHF7 mediates the ubiquitination of ATG14, thereby reducing the number of aggresome-like structures in osteosarcoma U2OS cells." (PMID 41267209, 2026). "Findings of the present study showed that Atg14 is significantly upregulated in cisplatin-treated the Saos-2 osteosarcoma cell line." (PMID 24337183, 2014). "Ultimately, all these findings, through both genetic inhibition and overexpression of autophagy, indicated that Siglec-15-induced autophagy promoted the invasive and migratory ability of human osteosarcoma cells by targeting the EMT and Beclin-1/ATG14 pathway." (PMID 35842729, 2022). "In addition, the autophagy induced by Siglec-15 could promote EMT and affect cytoskeletal rearrangement through the effect of these two pathways, and Siglec-15-induced autophagy promoted the invasion and metastasis of human osteosarcoma cells via the Beclin-1/ATG14 pathways." (PMID 35842729, 2022). "Additionally, we demonstrated that Siglec-15 silencing reduced the expression of Beclin-1/ATG14, and Siglec-15-related autophagy could promote EMT and affect cytoskeletal rearrangement, through which Siglec-15-induced autophagy participated in the regulation of osteosarcoma cell metastasis." (PMID 35842729, 2022).
viral infection (4 papers, 2019 to 2025). "Knockdown of AMPK and genes encoding members of the phosphoinositide 3-kinase (PI3K) complex composed of the autophagy-related protein 14 (ATG14), BECN1, and vacuolar protein sorting 34 (VPS34) facilitated viral infection in leafhoppers." (PMID 40300033, 2025). "As few studies have examined the role of ATG14 in viral infection, we used the CRISPR-Cas9 gene-editing plasmid expressing a sgRNA targeting the first exon of ATG14 and examined its effects on CVB3 infectivity." (PMID 34440910, 2021). "To test the role of autophagy in virus infection, we used short hairpin RNAs (shRNAs) to silence autophagy genes, ATG12, ATG14, or Beclin1, in iSLK.219 cells." (PMID 31375594, 2019). "ATG14 and ZDHHC16 (zinc finger DHHC-type containing 16) may indicate the engagement of autophagy-related pathways and membrane trafficking adjustments as cellular strategies against viral infection." (PMID 38655085, 2024).
Insulin resistance (3 papers, 2018 to 2023). Increased resistance towards insulin, that is, diminished effectiveness of insulin in reducing blood glucose levels. "Our data supported that ATG14 is a direct target of miR199a-5p and that its role in the miR199a-5p cascade caused insulin resistance." (PMID 29540751, 2018). "Furthermore, we uncovered a novel mechanism whereby dysregulated miR199a-5p suppresses the expression of ATG14 and inhibits autophagy, which in turn leads to the downregulation of hepatic insulin sensitivity and eventually causes insulin resistance." (PMID 29540751, 2018). "Other studies have demonstrated that Atg14 can activate autophagy and overcome insulin resistance in human hepatoma carcinoma cells." (PMID 38006398, 2023). "In addition, ATG14 was reported to activate autophagy and overcome insulin resistance in human hepatoma carcinoma cells." (PMID 32727463, 2020). "Notably, overexpression of ATG14 alone improved insulin sensitivity in vivo, suggesting a role of autophagy in insulin resistance." (PMID 29540751, 2018).
multiple myeloma (3 papers, 2020 to 2021). "In MM, ATG14 was discovered to be up-regulated, knockdown of ATG14 reduced cell proliferation and induced apoptosis, thus sensitizing myeloma cells to melphalan." (PMID 34930344, 2021). "Among them, LINC00515 was reported to promote multiple myeloma autophagy and chemoresistance though the miR-140-5p/ATG14 axis." (PMID 32670393, 2020). "Therefore, together with our data herein, multiple genes in the autophagy pathway have been shown to be regulated by miRNAs, including targeting of ATG2B by miR-130 in chronic lymphocytic leukemia and ATG14 by miR-140 in multiple myeloma." (PMID 33076962, 2020).
cervical cancer (2 papers, 2022 to 2025). A primary or metastatic malignant neoplasm involving the cervix. "Another study has shown that a supernatant cultured with L. crispatus and L. rhamnosus can reduce the expression of autophagy genes ATG14, BECN1, and HPV E6 oncogene to create an anti-proliferative effect on HeLa cervical cancer cells." (PMID 35800388, 2022).